CD109 (CD109 molecule)
Diseases named in the same sentence as CD109 in open-access papers (continued):
Sharing a sentence is not in itself a finding about the gene and the disease.
pancreatic cancer (6 papers, 2014 to 2024). "Our results suggest that these two novel mAbs are excellent tools for determining the expression level of CD109 in the tumour specimens and sera of patients with a wide range of cancers, in particular pancreatic cancer, and for investigating its diagnostic, prognostic and predictive value." (PMID 29731998, 2018). "MS analysis of glycopeptides captured from the surface of BxPC-3 cells revealed the presence of glycoproteins previously associated with pancreatic cancer (e.g., integrin beta-1, intercellular adhesion molecule 1) as well as novel pancreatic cancer cell-surface proteins (e.g., CD109)." (PMID 25635161, 2014). "The CD109 antigen recognised by these novel mAbs is located on the surface of human pancreatic cancer cells." (PMID 29731998, 2018). "Here, we report the generation of two mAbs, KU42.33C and KU43.13A, against two distinct epitopes on the external domain of CD109, using the human pancreatic cancer cell line BxPC-3 as the source of tumour immunogen." (PMID 29731998, 2018). "Here, we report the development of two novel mouse mAbs against distinct epitopes on the extracellular domain of CD109, using the human pancreatic cancer cell line BxPC-3 as the source of tumour immunogen." (PMID 29731998, 2018). "In only one study, Haun and colleagues examined the expression of CD109 in a panel of eight human pancreatic cancer cell lines by Western blot." (PMID 29731998, 2018). "Next, we examined the relative expression of CD109 antigen by mAb KU42.33C in human pancreatic cancer tissue arrays containing 70 specimens from patients with pancreatic adenocarcinoma." (PMID 29731998, 2018). "The varied expression of CD109 observed in the pancreatic cancer cell lines is thus very similar to the protein expression detected in human tumor specimens." (PMID 25635161, 2014). "Western analysis of CD109 in lysates prepared from pancreatic cancer cell lines revealed it was expressed in 6 of 8 cell lines, with a high level of expression in BxPC-3, MIAPaCa-2, and Panc-1 cells." (PMID 25635161, 2014). "Similar to the pancreatic cancer cell lines, variable CD109 protein expression was also observed in the pancreatic tumors, which is expected based on the genetic heterogeneity demonstrated among individual PDAC tumors." (PMID 25635161, 2014). "Immunohistochemical analyses of human pancreatic tissues indicate CD109 is significantly overexpressed in pancreatic tumors compared to normal pancreas." (PMID 25635161, 2014). "Using ELISA, flow cytometry, competitive assay and immunoprecipitation followed by mass spectrometry, we discovered that these two mAbs target two distinct epitopes on the external domain of CD109 that are overexpressed by varying amounts in human pancreatic cancer cell lines." (PMID 29731998, 2018). "In summary, our results suggest that high expression of CD109 is common in pancreatic cancer." (PMID 29731998, 2018). "A protein identified by the cell-surface glycoprotein capture procedure, CD109, was evaluated by western analysis of lysates of pancreatic cancer cell lines and by immunohistochemistry in sections of pancreatic ductal adenocarcinoma and non- neoplastic pancreatic tissues." (PMID 25635161, 2014). "MS/MS analysis of glycopeptides captured from BxPC-3 cells revealed 18 proteins predicted or known to be associated with the plasma membrane, including CD109, which has not been reported in pancreatic cancer." (PMID 25635161, 2014). "We found that the antigens recognised by these three novel mAbs were CD109, integrin α3 and CD26, with high levels of expression in several human pancreatic cancer cells and Pancreatic Cancer Tissue microarray." (PMID 33917882, 2021). "We showed that the CD109 antigen is overexpressed in several human pancreatic cancer cell lines and pancreatic cancer tissue array, with no expression in normal pancreatic tissues." (PMID 29731998, 2018).
pancreatic cancer (continued). "There is currently no comprehensive study on the expression pattern of CD109 determined by immunohistochemistry and its prognostic significance and predictive value for response to therapy in patients with pancreatic cancer." (PMID 29731998, 2018). "Since the expression of CD109 has not been thoroughly investigated in pancreatic cancer previously, we examined its expression in lysates of 8 pancreatic cancer cell lines by western analysis." (PMID 25635161, 2014). "Interestingly, immunohistochemistry of human pancreatic carcinoma tissue arrays with mAb KU42.33C showed that 94% of the 65 human pancreatic adenocarcinoma cases were CD109 positive, with no expression in normal pancreatic tissues." (PMID 29731998, 2018). "Similar to our findings, peptides corresponding to CD109 were also identified in a screen of proteins secreted from a pancreatic cancer-derived (Panc-1) and nonneoplastic pancreatic ductal cell line (HPDE), but expression of CD109 in pancreatic tumors has not previously been verified." (PMID 25635161, 2014).
scleroderma (6 papers, 2012 to 2026). Scleroderma is a rare autoimmune connective tissue disorder characterized by abnormal hardening of the skin and, sometimes, other organs. "CD109 is overexpressed in scleroderma and decreases fibrotic responses associated with the disease." (PMID 39990858, 2024). "As previously demonstrated by us, CD109 expression in scleroderma is significantly elevated in skin tissue and fibroblasts compared to healthy controls, likely as an adaptive response." (PMID 39990858, 2024). "The skin disorders in which CD109 has been shown to play a key role include lung fibrosis, scleroderma, psoriasis, and keloids." (PMID 39990858, 2024). "In the skin, CD109 modulates inflammation by influencing cytokine levels and immune cell recruitment, impacting conditions such as wound healing, psoriasis, and scleroderma." (PMID 39990858, 2024). "The laboratory of Anie Philip has reported that CD109 expression is elevated in skin samples from patients with systemic sclerosis (SSc)/scleroderma, as well as in skin fibroblasts cultured from SSc patients." (PMID 35892569, 2022). "In a separate study, CD109 over-expression in a mouse bleomycin-induced scleroderma model led to histological evidence of reduced skin fibrosis and a decrease in Smad2/3 phosphorylation." (PMID 35892569, 2022). "CD109 is also expressed in keratinocytes and contributes to the inhibition of extracellular matrix production in scleroderma." (PMID 24376795, 2013). "Given its dysregulation in fibrotic disorders such as scleroderma, our results identify CD109 as a key regulator of skin homeostasis by modulating ECM production and fibroblast activation, underscoring its potential as a therapeutic target in fibrotic disorders." (PMID 41898693, 2026). "A link between CD109 expression and inflammation in scleroderma remains to be established." (PMID 39990858, 2024). "The team hypothesized that the elevation of CD109 in SSc patients may thus represent an adaptation to elevated TGFβ signaling, with potential value to reduce fibrotic disease as supported by the in vivo mouse scleroderma studies." (PMID 35892569, 2022).
acute myeloid leukemia (5 papers, 2012 to 2024). Acute myeloid leukemia (AML) is a group of neoplasms arising from precursor cells committed to the myeloid cell-line differentiation. "HL-60 was studied and characterized previously for Acute myeloid leukemia studies and the expression of pattern of CD109 and LRP12 could confirm its validation." (PMID 36299526, 2022). "Originally identified by mAbs raised against the primitive CD34+ acute myeloid leukaemia cell line KG1a, CD109 is a transforming growth factor (TGF)-β co-receptor that binds TGF-β1, regulates TGF-β receptor endocytosis and degradation, and suppresses TGF-β/Smad signalling." (PMID 29731998, 2018). "CD109 has also been reported as the cell surface antigen on acute myeloid leukemia." (PMID 24376795, 2013). "CD109 has emerged as a potential biomarker for Acute Myeloid Leukemia (AML), playing crucial roles in immune attention and inflammation." (PMID 39990858, 2024). "Another gene of interest highlighted by this analysis is CD109 (chromosome 6), a cell surface antigen which was initially studied in CD34 positive acute myeloid leukaemia cell lines, but has subsequently been found to be expressed on a variety of haematopoietic cells and endothelial structures." (PMID 22311740, 2012).
rheumatoid arthritis (5 papers, 2023 to 2025). A chronic, systemic autoimmune disorder characterized by inflammation in the synovial membranes and articular surfaces. "In synovial tissue, CD109 drives inflammation in rheumatoid arthritis by regulating cytokine production and signaling." (PMID 39990858, 2024). "CD109 is mostly expressed in activated T cells and platelets and its overexpression is connected with tumor progression, fibrosis and rheumatoid arthritis." (PMID 36809715, 2023). "As inflammatory properties of CD109 have been proven in the context of the systemic autoimmune chronic disease, rheumatoid arthritis, the mechanism of chronic events in urticaria might be of a less severe, fibroblast-independent nature." (PMID 37371632, 2023). "Additionally, cluster of differentiation 90 (CD90) and CD109 transmembrane proteins, upregulated as OA progresses, regulate the pathological response in rheumatoid arthritis (RA) fibroblast-like synoviocytes, driving inflammation and fibrosis." (PMID 38298208, 2024). "CD109 facilitates the activation and recruitment of leukocytes by promoting the production of CXCL-9 and CXCL-10 in rheumatoid arthritis FLSs." (PMID 39990858, 2024). "CD109 interacts with enolase 1 (ENO1), which activates p38 MAPK and NF-κB pathways, thus leading to elevated levels of pro-inflammatory mediators involved in rheumatoid arthritis." (PMID 39990858, 2024).
soft tissue sarcoma (5 papers, 2013 to 2018). A malignant neoplasm arising from muscle tissue, adipose tissue, blood vessels, fibrous tissue, or other supportive tissues excluding the bones. "High expression of CD109 is associated with unfavorable prognosis in diffuse large B-cell lymphoma (DLBCL), soft tissue sarcoma and several other cancers." (PMID 30050054, 2018). "Subsequently, we evaluated the expression of CD109 protein in 80 clinical specimens of soft tissue sarcoma." (PMID 24376795, 2013). "To determine the clinical relevance of CD109 expression in soft tissue sarcomas (STS), we evaluated CD109 expression by immunohistochemistry in the primary extremity lesions of 80 STSs." (PMID 24376795, 2013). "In addition, a strong correlation was detected between CD109 expression and prognosis in soft tissue sarcomas and TNBC." (PMID 27419372, 2016).
triple-negative breast carcinoma (5 papers, 2016 to 2023). An invasive breast carcinoma which is negative for expression of estrogen receptor (ER), progesterone receptor (PR), and human epidermal growth factor receptor 2 (HER2). "CD109 expression was also found to be greater in triple-negative breast cancer (TNBC) compared to non-TNBC and to be associated with higher rate of distant metastasis and worse postoperative disease-specific survival compared to those with low or no expression." (PMID 29731998, 2018).
urothelial carcinoma (5 papers, 2013 to 2018). A malignant neoplasm derived from the transitional epithelium of the urinary tract (urinary bladder, ureter, urethra, or renal pelvis). "In contrast, CD109 expression was associated with better prognosis in patients with urothelial carcinomas." (PMID 29731998, 2018). "Although it is reported that CD109 is preferentially expressed in the early stage of tumorigenesis in oral tumor and urothelial carcinomas, we demonstrated that high expression of CD109 was significantly associated with advanced stage in STSs." (PMID 24376795, 2013). "Thus, we propose that CD109 could become a urine-based marker for urothelial carcinoma of the urinary tract." (PMID 24400073, 2014).
cervical carcinoma (4 papers, 2018 to 2022). A carcinoma arising from either the exocervical squamous epithelium or the endocervical glandular epithelium. "C4-1, CaSki and SiHa cells with high CD109 expression were chosen for functional study using a loss-of-gene function approach through siRNA knockdown to determine whether CD109 is physiologically relevant in cervical cancer." (PMID 32507856, 2020). "As CD109 is strongly expressed in cervical squamous cell carcinoma, this study was conducted to investigate its functional characteristics in cervical cancer." (PMID 32507856, 2020). "Our finding suggested that the expression level of CD109 protein was significantly different among various histological classifications of cervical cancer." (PMID 32507856, 2020). "By IHC analysis of two cervical tissue microarrays (CXC1501 and CXC1502), we determined the expression level of CD109 protein in 10 normal–benign cervical tissue samples and 140 cervical carcinoma tissue samples." (PMID 32507856, 2020). "CRISPR KO of CD109 expression reverses the in vitro and in vivo tumorigenic and cancer-aggressive capability of cervical cancer cells." (PMID 32507856, 2020). "Meanwhile, cervical cancer cell lines with high CD109 expression were chosen for the functional study using siRNA knockdown and CRISPR/Cas9 knockout." (PMID 32507856, 2020). "(2020) demonstrated that targeting CD109 by siRNA or CRISPR/Cas9 could inhibit cervical cancers’ tumorigenic and aggressive properties by inactivating the CD109/EGFR/STAT3 axis in vitro and in vivo." (PMID 35508982, 2022). "However, the detailed mechanisms on how CD109 proteins promote tumour aggressiveness in cervical cancer are not clearly understood." (PMID 32507856, 2020). "Abundant CD109( + ) populations in cervical cancer cells potentially contributed to carcinogenesis and aggressiveness, whereas silencing of CD109 expression could reverse those properties." (PMID 32507856, 2020). "Therefore, we further investigate the functional role of CD109-expressing cells and their tumorigenic characteristics in cervical cancer." (PMID 32507856, 2020). "CD109 is drastically expressed in cervical cancer and upregulates epidermal growth factor receptor (EGFR)-mediated STAT3 phosphorylation, enabling cervical cancer cell migration and proliferation, and supporting cancer cell phenotype." (PMID 35508982, 2022). "Whilst blockade of CD109 by siRNA and CRISPR/Cas9 inhibited STAT3 activation in cervical cancer cell lines." (PMID 32507856, 2020). "However, the functional role of CD109 in cervical cancer remains unknown." (PMID 32507856, 2020). "To investigate whether CD109 facilitates the EGFR/STAT3 signalling, we performed a Western blot analysis to determine the expression of CD109 and EGFR, and the phosphorylation of STAT3 in different cervical cancer cell lines." (PMID 32507856, 2020). "Also, CD109, as a result of its role in transforming growth factor-β1 (TGF-β1) signaling and signal transducer and activator of transcription 3 (STAT3) activation, could be an innovative target for cervical cancer therapy." (PMID 35508982, 2022).
cervical squamous cell carcinoma (4 papers, 2020 to 2023). A squamous cell carcinoma arising from the cervical epithelium. "To examine the physiological relevance of CD109 with cervical squamous cell carcinoma, we knocked down CD109 expression in C4-1, CaSki and SiHa cells using siRNA." (PMID 32507856, 2020). "Our findings suggested that CD109 protein was frequently overexpressed in cervical squamous cell carcinoma." (PMID 32507856, 2020). "In cervical squamous cell carcinoma, CD109 expression enhanced EGFR-induced phosphorylation of STAT3, resulting in increased tumor aggressiveness and stemness activity." (PMID 33375719, 2020). "CRISPR/Cas9 knockout of CD109 can abolish the tumorigenic and aggressive effects, which was highlighted in cervical squamous cell carcinoma." (PMID 32507856, 2020). "CD109 protein was more frequently expressed in cervical squamous cell carcinoma than other histological types of carcinoma." (PMID 32507856, 2020). "Firstly, we found that high expression level of CD109 protein was also observed in cervical squamous cancer tissues in IHC analysis." (PMID 32507856, 2020). "Moderate-to-strong CD109 staining was observed at the cellular membrane within cervical squamous cancer cells, while weak CD109 staining was displayed in normal–benign cervical tissue." (PMID 32507856, 2020). "For cervical squamous cell carcinomas, as high expression level of the CD109 gene can also be detected, CD109 would be considered as a potential molecular target for the development of new therapies." (PMID 32507856, 2020). "IHC demonstrated an upregulation of CD109 in the cell membrane of cervical squamous cell carcinoma." (PMID 32507856, 2020). "CD109 expression is frequently detected in cervical squamous cell carcinoma." (PMID 32507856, 2020). "In cervical squamous cell carcinoma, CD109 expression enhanced aggressiveness and maintained cancer stemness properties through the EGFR-STAT3 signaling cascade, suggesting the potential role of CD109 as a diagnostic cancer marker and therapeutic target." (PMID 33375719, 2020). "Our findings indicated that CD109 facilitates tumorigenicity and cancer aggressiveness, which might be mediated by EGFR/STAT3 signalling in cervical squamous cell carcinoma." (PMID 32507856, 2020). "Moreover, CD109 is responsible for the induction of EGFR-mediated STAT3 regulation in cancer tumorigenicity and aggressiveness, which might reveal a potential molecular target for the development of an effective therapeutic strategy against cervical squamous cell carcinoma." (PMID 32507856, 2020).
leukemia (4 papers, 2013 to 2025). A malignant (clonal) hematologic disorder, involving hematopoietic stem cells and characterized by the presence of primitive or atypical myeloid or lymphoid cells in the bone marrow and the blood. "Finally, public RNA-seq data from 93 leukemia cell lines for the identified NKX6-3 target genes show reduced activity of CD109 and overexpression of GP5 and MPP7 in RCH-ACV and MHH-CALL-3, highlighting the suitability of these cell lines as models for their investigation in follow-up studies." (PMID 41153416, 2025). "CD109, a GPI-anchored glycoprotein, was originally identified as a leukemia antigen." (PMID 24376795, 2013). "We evaluated the HPA genotype and/or the CD109 mRNA expression on two peripheral blood stem cells (PBSC), two peripheral bloods (PB), 12 granulocyte products, natural killer (NK)-92, B-lymphocyte (CO88BV59-1), K-562 leukemia cell line, human embryonic stem cell (hESC), and human fibroblasts (HF)." (PMID 23509816, 2013).
malignant melanoma (4 papers, 2016 to 2021). "Levels of ATM1, AMFR, SOS1, and CD109 gene fragments were up-regulated (p < 0.001) in melanoma samples (n = 144) compared to healthy controls (n = 41) (AUC = 0.825)." (PMID 30634628, 2019). "We measured levels of SOS1, ATM1, CD109, and AMFR mRNA fragments in plasma samples from 173 melanoma patients and 47 healthy controls." (PMID 30634628, 2019). "Levels of ATM, AMFR, CD109, and SOS1 were all significantly higher (p < 0.001) in plasma samples from either stage 0, stage I/II, or stage III/IV melanoma patients than in healthy controls (respectively), consistent with the NGS data (Table A1)." (PMID 30634628, 2019).
pancreatic ductal adenocarcinoma (4 papers, 2014 to 2023). An infiltrating adenocarcinoma that arises from the epithelial cells of the pancreas. "Contrarily, a recent study argued that CD109 suppression did not affect YAP downstream gene expressions in pancreatic ductal adenocarcinoma cells." (PMID 33375719, 2020).